TNF (tumor necrosis factor)
Diseases named in the same sentence as TNF in open-access papers (continued):
Sharing a sentence is not in itself a finding about the gene and the disease.
congestive heart failure (continued). "In a cohort of patients with congestive heart failure, n-3 PUFA supplementation for three months was associated with a significant decrease in serum IL-6 and TNF-α levels, but not in CRP levels, which actually decreased only in smokers." (PMID 27043616, 2016). "Clinical trials assessing PTX in chronic heart failure showed no concordant action on downmodulation of TNF levels, despite clinical improvement and beneficial effects on biomarkers of heart lesion." (PMID 25789471, 2015). "Regarding AEs of special interest with respect to TNF blockade, there were no cases of congestive heart failure-related AEs, demyelinating disease, lupus-like syndrome, malignancies, opportunistic infections/TB, blood dyscrasias, or deaths." (PMID 24487484, 2014). "In the circulatory system, TNF-α is responsible for many myocardial diseases such as acute coronary syndrome, Acute myocardial infarction (AMI), myocarditis, dilated cardiomyopathy and congestive heart failure (CHF)." (PMID 21450068, 2011). "However, in their 2018 study, Mao et al34 reported that forest bathing reduced the level of TNF-α, but not IL-6, in elderly patients with chronic heart failure." (PMID 40673365, 2025). "Furthermore, several studies have shown that the use of tumor necrosis factor-alpha inhibitors (TNFi) in patients with RA has led to improvement in CVD with primary endpoints being congestive heart failure, nonfatal myocardial infarction, and lipid profiles." (PMID 35915691, 2022). "In addition, 16 weeks of combined aerobic and resistance exercise training decreased both TNF receptors (but not TNF-α itself) in patients with chronic heart failure." (PMID 33936044, 2021). "However, in our study, we did not found a significant relationship between HRV and TNF-alpha in healthy volunteers; a similar observation has also been recently reported in patients with chronic heart failure." (PMID 25207649, 2014). "However, recent data has suggested that inflammatory biomarkers such as IL-6, TNF-alpha, hsCRP, fibrinogen, and BNP are not predictive of intermediate-term risk of ventricular tachyarrhythmias in stable chronic heart failure." (PMID 22203916, 2011). "However, recent data has suggested that inflammatory biomarkers such as IL-6, TNF-alpha, hsCRP, and BNP are not predictive of intermediate-term risk of ventricular tachyarrhythmias in stable chronic heart failure." (PMID 20885777, 2010). "Additionally, in the ATTACH (Anti-Tnf alpha Therapy Against Chronic Heart failure) short-term trial, TNFα antagonism using infliximab did not ameliorate, and high doses increased the risk of HF-related hospitalization or death of patients affected by moderate-to-severe chronic HF." (PMID 36902036, 2023). "On the other hand, Mao et al33 in 2017 reported that forest bathing reduced the level of IL-6, but not TNF-α and CRP in elderly patients with chronic heart failure." (PMID 40673365, 2025). "Although we did not examine the concentration of TNF-α nor long-term outcomes, the correlation between CONUT score and inflammation was also shown in the present study as well as those with chronic heart failure." (PMID 32094392, 2020). "However, it was reported that the NP levels in patients with chronic heart failure were increased without IFN-γ elevation and correlated with TNF-α." (PMID 35529699, 2022).
ulcer (183 papers, 2007 to 2026). "These inflammatory mediators heighten the risk of GIB through two primary mechanisms: TNF-α promotes endothelial cell apoptosis and microvascular remodeling, whereas IL-6 impedes ulcer healing." (PMID 40687126, 2025). "It has been established that EGF, VEGF, IL-6, and TNF-α are crucial factors in the development of gastric ulcers, and their levels are associated with the healing or deterioration of these ulcers." (PMID 38398633, 2024). "Inducing ulcers using acetic acid caused the TNF-α level to increase significantly, by 155% at p < 0.0001 in comparison with the control group, indicating that the animal models were reproduced successfully." (PMID 35161436, 2022). "TNF-α can cause an accumulation of a large number of neutrophils around the ulcer, resulting in gastric microcirculation disturbance and the formation of gastric mucosal ulcer." (PMID 34335857, 2021). "TNF-α is also a powerful ulcer-causing medium that can promote the secondary release of other cytokines including IL-1, IL-6, IL-8, PAF, and PGs." (PMID 30719066, 2019). "TLR4 and RAGE deficiency enhanced ulcer healing and reduced the level of TNFα, whereas ulcer healing in TLR2 knockout (KO) mice was similar to that in wild-type mice." (PMID 24244627, 2013). "Pretreatment of ethanol-injected rats with both omeprazole and manuka honey caused a significant decrease in plasma TNF-α (38% and 28%) (P = 0.000 and 0.000), IL-1β (49% and 50%) (P = 0.000 and 0.000), and IL-6 (45% and 47%) (P = 0.000 and 0.000) as compared to the ulcer-induced rats." (PMID 26770649, 2016). "As an inflammatory cytokine, TNF-α can cause a second release of other cytokines and activate neutrophils and endothelial cells that affect the mucosal blood oxygen supply, which may eventually lead to the formation of ulcers." (PMID 29849711, 2018). "In an in-vivo oral mucositis model, the microneedle system accelerated mucosal healing, normalized inflammatory and angiogenic markers (VEGF, TNF-α, NF-κB, and IL-10), and achieved nearly complete ulcer recovery when compared to standard treatments." (PMID 40676449, 2026). "A chemically induced ROU model in rats (n = 8 per group) was established to evaluate the effects of AF-SD on ulcer area, serum inflammatory cytokines (TNF-α, IL-6), vascular endothelial growth factor (VEGF) levels, and histopathological outcomes." (PMID 41599609, 2025). "In studies of indomethacin‐induced ulcer, it was reported that the level of TNF‐α increased by indomethacin." (PMID 40746654, 2025). "The levels of pro-inflammatory factors such as NF-κB, TNF-α, and IL-6, which trigger inflammation and slow ulcer healing, also increase with ethanol consumption." (PMID 40244034, 2025). "The ulcer control rats showed the highest inflammation rate represented by higher TNF‐α, IL‐6 cytokines, and lower IL‐10 levels compared to all groups." (PMID 40034223, 2025). "The reference rats showed a better serum inflammatory profile (lower TNF‐α, and IL‐6 levels and increased IL‐10 cytokines) than the ulcer controls." (PMID 40034223, 2025). "Chrysin oral gel (1% and 2%) application for 7 days decreased buccal contents of TNF-α by 51% and 71%, NF-κβ by 22% and 60%, and IL-6 by 49% and 78%, respectively, as compared to the ulcer group." (PMID 40809172, 2025). "Together, these results demonstrate that AF-SD effectively suppressed ulcer-induced upregulation of the pro-inflammatory cytokines TNF-α and IL-6, exhibiting a superior anti-inflammatory effect compared with the clinically used spray." (PMID 41599609, 2025). "Regarding the Omeprazole treatment group, there was a significant decrease in TNF-α and IL-6 levels compared to the ulcer induction group (G2)." (PMID 40469801, 2025). "The group that received cranberry treatment (G4) demonstrated a noteworthy reduction in the levels of TNF-α and IL-6 when compared to the levels that were observed in the group that was subjected to Indomethacin ulcer induction (G2)." (PMID 40469801, 2025).
ulcer (continued). "mRNA levels of IL-1β, IL-6, IL-18, and TNF-α in the ulcer tissue were significantly reduced following butyrate treatment, while the levels of tight junction proteins Claudin-1 and ZO-1 were significantly elevated." (PMID 40818135, 2025). "One of the most significant pro‐inflammatory cytokines involved in this inflammation is tumor necrosis factor (TNF)‐α During the ulcer, neutrophil infiltration is observed in the gastric mucosa." (PMID 40746654, 2025). "To evaluate the anti-inflammatory effect of the CHRs on ulcers, we measured the levels of pro-inflammatory cytokines, including TNF-α, IL-6, IL-18, and IL-12 in the serum." (PMID 40283949, 2025). "The mechanisms of gastric injury have not been fully clarified, but it is well known that pro-inflammatory mediators, including IL-6, IL-12, TNF-α, and NF-κB, play an important role in the development of ulcers." (PMID 40283949, 2025). "TNF-α, IL-6, and IL-10 are significantly higher in ulcer control group compared to the fed with omeprazole or Schiff base compound." (PMID 39830532, 2024). "Ulcer model group had significantly higher blood levels of TNF‐α and IL‐6 (98.5%, p < 0.05 and 111.6%, p < 0.05, respectively) than control group." (PMID 39723096, 2024). "This study emphasizes the ability of PRF-EMFs to modulate the TGFβ, COX2, IL6, IL1β, and TNFα gene expression in exposed ulcers." (PMID 38671778, 2024). "Rats treated with Schiff base compound meaningfully condensed TNF-α and IL-6, increased IL-10 quantities, and related ulcer control group." (PMID 39830532, 2024). "This faster healing on the tongue was further supported by significantly lower expression levels of TNF-α and IL-1β and a reduction in ulcer size, particularly on the tongue compared to the palate." (PMID 39739075, 2024). "AA showed severe macroscopic colonic lesions associated with increased ulcer number, area, and severity with significantly elevated PI3K, p-Akt, Nrf2, TNF-α, and IL-6 in colorectal tissue as compared to the normal control group." (PMID 38645494, 2024). "TNF-α deactivates the TJs and induces the apoptosis of epithelial cells, thus negatively affecting the barrier function and ulcer repair." (PMID 38397811, 2024). "In agreement with the literature, a more intense expression of COX2, IL1β, IL6, TGFβ, and TNFα was observed in ulcer-HDFs than in normal-HDFs." (PMID 38671778, 2024). "As a result, suppressing the expression of pro-inflammatory cytokines such as TNF-α, IL-1β, and IL-6 effectively treats ulcer damage in the colon." (PMID 38791116, 2024). "Gastric TNF-α level was further reduced by NS-398 as compared to NPW-treated ulcer group (p < 0.05), while gastric IL-1β levels were depressed more with both of the specific COX-inhibitors (p < 0.05–0.01)." (PMID 38227096, 2024). "Compared to the ulcer group, the Cls and Omp groups had significant reductions in IL-1β, IL-6, and TNF-α contents." (PMID 38884677, 2024). "Meanwhile, AR can prevent the damage of gastric mucosa induced by indomethacin and promote ulcer healing through reducing TNF-α, IL-1β, and MPO, and increasing the PGE2 in the gastric tissue." (PMID 37109624, 2023). "Considering that the inflammatory cytokine is a severe resistance to the healing of ulcers, TNF-α immunostaining was conducted to investigate the anti-inflammatory effect of GCN." (PMID 37288357, 2023). "It regulates expression of genes of the inflammatory pathway like TNF-α and IL-6, increasing inflammation and extension of ulcer injury." (PMID 37255094, 2023). "This study agrees with all previous findings that implicate TNF-α level is remarkably augmented in serum and stomach tissue of ethanol-influenced ulcers." (PMID 38021520, 2023). "TNF-α production was directly proportional to indomethacin dosage and was closely related to ulcer area, and inhibition of TNF-α synthesis can significantly reduce small intestinal ulcers." (PMID 35222032, 2022).
ulcer (continued). "In normal skin wounds, TNF-α is quickly released by the vascular endothelium of the ulcer areas, and it initiates the inflammatory process for wound healing." (PMID 35836916, 2022). "As compared to both the ulcer and the pre-treated group, mice treated with EGb 761 after indomethacin-induced ulceration exhibited a marked decrease in TNF-α expression." (PMID 36080365, 2022). "Our results are in agreement with the results of the studies conducted on mouse models of the H. pylori-infection, which demonstrated that the TNF-α mRNA expression were significantly greater in the PUD group than in the non-ulcer group." (PMID 36057049, 2022). "TNF-α and IL-6 apparently rose by 58.8% and 68.1% in the ulcer control group compared to those in the normal control group (p < 0.01)." (PMID 35938492, 2022). "While the group treated with ZJP (1, 2, and 4 g/kg) displayed a noteworthy decrease in TNF-α and IL-6 content (P < 0.01) in a dose-dependent mode referred to ulcer model group." (PMID 35938492, 2022). "MD-4 significantly (p < 0.05) increased the superoxide dismutase (SOD) levels in ulcers and reduced pepsin, TNF-α, and IL-6 levels." (PMID 36292625, 2022). "The NLRP3 inflammasome, an important proinflammatory mediator that is involved in ulcer pathogenesis, is activated by binding to PRRs, which increases the expression of pro-IL-1β and pro-TNF-α, thereby damaging the gastric mucosa." (PMID 36275647, 2022). "TNF-α blocks gastric microcirculation around the mucosa of the ulcer, further delaying ulcer healing." (PMID 36275647, 2022). "We analyzed the ulcer area, conducted histological analysis, and measured the levels of the inflammatory cytokines TNF-α, IL-6, IL-1β, and IFN-γ, and anti-inflammatory cytokine IL-10 by ELISA." (PMID 35456589, 2022). "For mice that were treated with EGb 761 orally following indomethacin-induced ulcerations, the levels of TNF-α (173.7 ± 10.98 pg/mL, p < 0.001) and the levels of IL-6 (188.8 ± 21.71 ng/L, p < 0.01) were considerably lowered as compared to the ulcer group." (PMID 36080365, 2022). "When compared to the ulcer group, prophylactic treatment with EGb 761 attenuated the elevation of the gastric tissue cytokines; TNF-α (178.3 ± 9.72 pg/mL, p < 0.001) and IL-6 (230 ± 13.73 ng/L, p < 0.001)." (PMID 36080365, 2022). "The results demonstrated that ZJP suppressed the inflammatory response to alleviate ulcers in gastric tissue by decreasing the content of TNF-α and IL-6 and restraining neutrophil infiltration of the ulcer gastric tissue." (PMID 35938492, 2022). "The exacerbated expression of IL-1β contributes to the formation of ulcers and stimulates the production of more TNF-α." (PMID 34497525, 2021). "In contrast with control cohort, the amounts of IL-1β, IL-6, TNF-α, IL-18 in ulcer model cohort increased to 8.52-, 5.24-, 7.86-, and 4.16-folds, respectively." (PMID 34975497, 2021). "TNF-α expression was significantly lower in ulcers treated with extracts of Chamomilla recutita, Salvadora persica and Koyanqing Granule formula, compared to controls." (PMID 34667500, 2021). "The examined levels of TNF-α in gastric tissue were found to be highly expressed in the ethanol-induced ulcer model while in the 4α,24-dimethyl-5α-cholest-8β,18-dihydroxy,22E-en-3β-ol isolated from Nephthea sp." (PMID 34439913, 2021). "The mechanisms of gastric injury have not been fully clarified, but it is well known that proinflammatory mediators played an important role in the development of ulcer, including IL-6, IL-10, tumor necrosis factor-α (TNF-α), and NF-κB." (PMID 34580595, 2021). "For RAS patients, an in vitro study has shown that TNF-α was higher in unstimulated peripheral blood monocytes from RAS patients with ulcers than in HCs." (PMID 35003055, 2021). "The expression of IL-6 and TNF-α in serum in the three induced stress ulcer groups was increased compared with the normal group, indicating that overexpression of inflammatory factors occurs during gastric mucosal injury." (PMID 33628315, 2021).
ulcer (continued). "This oral gel can improve ulcer wound healing through the role of TNF-α and collagen with the same results as topical steroid therapy." (PMID 41018047, 2021). "Among them, topical application of infliximab, an anti-TNFα Ab, has been described in patients with ulcers, and Flightless I (Flii) neutralizing antibodies (FnAb) have been applied in a murine model of epidermolysis bullosa acquisita." (PMID 34281610, 2021). "Quantitative analysis showed an increase in area (%) of TNF-α protein expression in ethanol-induced ulcers compared with control and other pretreated and treated rats." (PMID 34829707, 2021). "Evidence from clinical studies suggests that DFU patients with ulcers that fail to heal show higher serum TNF-α levels." (PMID 33981238, 2021). "Pre-treatment with C. conglomeratus alcohol extract significantly reduced galactin-3, and TNF-α in ethanol-induced ulcer model at 25, 50, and 100 mg/kg." (PMID 32942704, 2020). "In L. braziliensis patients, the positive correlation was observed between TNF level and ulcer size and suggested TNF inhibitors can improve healing process in CL patients with severe lesions." (PMID 33004861, 2020). "F-AOH effectively reduced the ulcer index (from 23.4 ± 4.28 to 8.32 ± 1.5) and reduced release of inflammatory mediators (IL-1β, IL-6, TNF-α and PGE2), increased the content of nitric oxide and improved GAS and MTL secretion." (PMID 32871094, 2020). "The positive ulcer group showed a marked increase in NF-kB, and TNF-α tissue levels by 2.4 and 5.3 folds respectively as compared to the control group (respectively)." (PMID 31404064, 2019). "Positive-feedback loops between some of these molecules, as the activation of NF-κB by TNF-α or MMP1 and MMP3 by TNF-α and IL-1β, further amplify the activated signalling pathways finally leading to the mucosa damage or ulcer." (PMID 31581434, 2019). "Cytokines IL-8 and TNF-α play an important role in acute gastric mucosal injury and have a broad impact on the formation, development, and treatment of ulcer." (PMID 30719066, 2019). "TNF-α reduces gastric microcirculation around the ulcer and delays healing due to its ability to potentiate the inflammatory response." (PMID 29695040, 2018). "The tested preparation of potato juice significantly inhibited the induced secretion of TNF-α in rats administered 200 and 500 mg/kg b.w., by 52% and 35%, respectively, as compared to the ulcer-induced rats." (PMID 29495317, 2018). "In the current study, we evaluated the levels of IL-1, IL-6, IL-8, and TNF-α of the secretions of ulcer surface at different time points during the treatment." (PMID 29234410, 2017). "The expressions of IL-1, IL-6, IL-8, and TNF-α in the ulcer surface secretions of all samples were increased at the early stage of ulcer formation." (PMID 29234410, 2017). "Immunoblotting results confirmed that the ethanol-induced ulcer control group exhibited significant reductions in IL-4 (5.96-fold) level and increases of NF-κB p65 (10.50-fold), TNF-α (2.66-fold), and MCP-1 (3.06-fold) levels compared to the normal group." (PMID 28587230, 2017). "TNF-α, a potent stimulator of neutrophil infiltration, can activate the neutrophils to greatly accumulate around the ulcer." (PMID 28717228, 2017). "Activation of nuclear factor-kappaB (NF-κB) is a vibrant pathophysiological process during ulcer formation, which stimulates pro-inflammatory cytokines, such as TNF-α and IL-1β." (PMID 28587230, 2017). "Mixed cell implantation in this ulcer model reduced TNF-α and IL-6 levels in the tissues surrounding the mixed cell sheet-treated ulcers compared with controls or mice treated with trafermin (FGF2)." (PMID 28687753, 2017). "Recently, a positive correlation between ulcer size at the time of the first evaluation and TNF-α levels was observed, supporting the use of TNF inhibitors combined with standard therapy to improve recovery time in CL patients with severe lesions." (PMID 25325049, 2014).